USH1C (USH1 protein network component harmonin)
Description:
Anchoring/scaffolding protein that is a part of the functional network formed by USH1C, USH1G, CDH23 and MYO7A that mediates mechanotransduction in cochlear hair cells. Required for normal development and maintenance of cochlear hair cell bundles (By similarity). As part of the intermicrovillar adhesion complex/IMAC plays a role in brush border differentiation, controlling microvilli organization and length. Probably plays a central regulatory role in the assembly of the complex, recruiting CDHR2, CDHR5 and MYO7B to the microvilli tips.
Synonyms: PDZ73; harmonin; NY-CO-37; NY-CO-38; PDZ-73; AIE-75; PDZD7C; DFNB18; DFNB18A; PDZ-45; PDZ-73/NY-CO-38; ush1cpst
Tractability: Small molecule: a structure with a bound ligand is known. Antibody: its Gene Ontology location is reachable by antibodies, with medium confidence.
Gene: Protein-coding gene on chromosome 11 (17,493,895 to 17,544,416, reverse strand). Ensembl gene ENSG00000006611.
Subcellular location: Cytoplasm, cytosol; Cytoplasm, cytoskeleton; Cell projection, microvillus
Subcellular location (Human Protein Atlas): Cytosol
Pathways (Reactome):
Sensory Perception: Sensory processing of sound by inner hair cells of the cochlea; Sensory processing of sound by outer hair cells of the cochlea
Gene Ontology:
Molecular function: protein binding; spectrin binding
Biological process: brush border assembly; equilibrioception; G2/M transition of mitotic cell cycle; photoreceptor cell maintenance; protein localization to microvillus; protein-containing complex assembly; sensory perception of light stimulus; sensory perception of sound; actin filament bundle assembly; auditory receptor cell morphogenesis; inner ear auditory receptor cell differentiation; inner ear morphogenesis; inner ear receptor cell stereocilium organization; parallel actin filament bundle assembly; regulation of microvillus length; retinal cone cell development; neuromuscular process controlling balance
Cellular component: apical part of cell; brush border; cytoplasm; cytosol; microvillus; cilium; photoreceptor inner segment; photoreceptor outer segment; plasma membrane; stereocilia ankle link complex; stereocilium; stereocilium tip; synapse; cytoskeleton
Genetic constraint (gnomAD): Loss-of-function variants: 90 observed, 122.45 expected, observed/expected ratio (o/e) 0.73, 90% interval 0.62 to 0.88. The upper end of that interval is the gene's LOEUF score, 0.88, which puts it in group 3 of 6, group 1 being the genes least tolerant of losing a copy. Missense variants: 1,165 observed, 1,170.4 expected, observed/expected ratio (o/e) 1, 90% interval 0.95 to 1.04. Synonymous variants: 461 observed, 440.47 expected, observed/expected ratio (o/e) 1.05, 90% interval 0.97 to 1.13.
Gene-disease validity (ClinGen):
ClinGen rates the evidence that USH1C causes each of these diseases.
Usher syndrome type 1 (autosomal recessive): Definitive. A syndrome characterized by congenital, bilateral, severe sensorineural hearing loss, abnormalities in the vestibular system, and adolescent-onset retinitis pigmentosa.
nonsyndromic genetic hearing loss (autosomal recessive): Limited.
Homologues: Orthologues: chimpanzee USH1C (99% identical), macaque USH1C (98% identical), dog USH1C (95% identical), guinea pig USH1C (93% identical), rabbit USH1C (93% identical), mouse Ush1c (93% identical), rat Ush1c (92% identical), pig USH1C (87% identical), tropical clawed frog ush1c (53% identical), zebrafish ush1c (43% identical). Paralogues in human: WHRN (20% identical), PDZD7 (18% identical).